IL22 (interleukin 22)
Diseases named in the same sentence as IL22 in open-access papers (continued):
Sharing a sentence is not in itself a finding about the gene and the disease.
asthma (continued). "The neutralization of IL-22 positively modulated eosinophil recruitment to the lungs in an ovalbumin (OVA)-induced asthma model." (PMID 37445595, 2023). "The studies with IL-22 in asthma are scarce and suggest that this cytokine negatively reduces the pro-allergenic role of dendritic cells (DC)." (PMID 37445595, 2023). "The bench model treats Fezakinumab, an anti-IL22 monoclonal antibody that downregulates the inflammatory genes signature on blood, sputum and even bronchial brushing of patients with mild-to-severe asthma." (PMID 37189844, 2023). "In an attempt to investigate the role of IL-22 in asthma, which is still controversial, we use IL-22 knockout mice to evaluate its role on airway inflammation, eosinophil survival and number of dendritic cells." (PMID 37445595, 2023). "Some other Th cell subsets such as Th9 and Th22 have been described by some laboratories as being involved in the secretion of IL-9 and IL-22, respectively, which are associated with airway inflammation and AHR in asthma." (PMID 37377958, 2023). "Their role in general inflammatory pathophysiology and more specifically in respiratory diseases and asthma has rapidly been investigated and led to the concept of a “Th17 pathway” and Th17-type cytokines (IL-17, IL-17F, and IL-22)." (PMID 35386663, 2022). "Although the involvement of IL-22 in asthma seems very likely, its exact role is still to be clarified." (PMID 35386663, 2022). "In peripheral blood of asthmatic patients and preclinical asthma models, serum IL-22 levels are increased." (PMID 35967401, 2022). "Accordingly, we also found high levels of IL-17 and IL-22 in a mouse model of dog-allergen induced asthma characterized by a strong airway remodeling." (PMID 35386663, 2022). "Out of the field of asthma, IL-17 and IL-22 enhance airway remodeling in murine models of lung injury by pollutants (airway neutrophilic infiltration, epithelial desquamation, subepithelial fibrosis)." (PMID 35386663, 2022). "More recently, a specific subset of innate lymphoid cells (ILC), named ILC3, has emerged as another important local cellular source of IL-17 and IL-22, especially in asthma." (PMID 35386663, 2022). "The recent studies have indicated IL-22 can induce the occurrence of asthma in preclinical models, but it can ameliorate inflammation during asthma exacerbation." (PMID 35967401, 2022). "As a consequence, the role of IL-17 and IL-22 in asthma, has been questioned over the last two decades." (PMID 35386663, 2022). "Peripheral blood mononuclear cells from patients with severe asthma reportedly exhibit an enhanced capacity to synthesize IL-17A and IL-22 following in vitro activation." (PMID 35454142, 2022). "The vitro model of asthma treated with miRNA-221-5p mimic resulted in the reduction of IL-6, IL-17, IL-21 and IL-22 levels, and induction of IL-10, IL-35 and TGF-β levels." (PMID 34863307, 2021). "For instance, Th17 cells, the main cellular source of this cytokine, were refractory to inhibition with glucocorticoids in asthma, especially, when IL-17A and IL-22 were co-expressed in these cells." (PMID 33717165, 2021). "In summary, the present study clearly demonstrated the protective role of IL-22 in an OVA-induced asthma model." (PMID 34836520, 2021). "In view of the nonalignment of IL-22 roles in allergic asthma airway inflammation, we set out to investigate the role of IL-22 in the pathogenesis of allergic airway inflammation in asthma mouse model." (PMID 34836520, 2021). "It seems that T lymphocytes producing IL-22 are involved in the inflammatory infiltration of skin lesions in AD as well as in lung tissue in patients with asthma." (PMID 33435598, 2021). "Moderate asthma and severe asthma are usually related to the increase of neutrophils and Th17 cytokines such as IL-17A, IL-17F, and IL-22 producing the secretion of epithelial-derived neutrophil chemokines to attract neutrophils in the airways." (PMID 32015750, 2020).
asthma (continued). "In an asthma model of inflammation, the neutralization of IL-22 in the antigen challenge phase augmented expression of IL-17 and led to increased recruitment of neutrophils and eosinophils." (PMID 32637365, 2020). "In peripheral mononuclear cells from uncontrolled allergic asthmatics, AhR and IL-22 mRNA expression are increased compared with controlled asthma and healthy subjects, suggesting a relationship with asthma control." (PMID 33233810, 2020). "On the other hand, in conditions like hepatitis, asthma, inflammatory bowel disease and cholangitis, anti-inflammatory response of IL-22, to counteract the disparaging effect of immune response, has also been observed." (PMID 33042126, 2020). "To understand how miR-146a expression is regulated in the airway epithelial cells, we stimulated primary cultured HBECs from healthy donors with cytokines associated with asthma pathogenesis, including IFN-γ, TNF-α, IL-17A, IL-22 and IL-4." (PMID 31798831, 2019). "For example, increased serum IL-22 is found in asthma patients, where it seems to negatively regulate established allergic inflammation." (PMID 30978932, 2019). "TH17 cells also secrete IL-22, and IL-22 mRNA is elevated in PBMCs in pediatric patients with severe asthma, and rhinitis." (PMID 27746241, 2017). "Serum levels of IL-22 has been found to be elevated in the blood of asthmatic patients and lung tissues of asthma mouse model and to correlate with disease severity." (PMID 26772733, 2016). "Accumulating evidence indicates that Th17 cell and Th17 cytokines such as IL-17A, IL-17F and IL-22 contribute to the development of asthma." (PMID 26974537, 2016). "The aim of this study was to evaluate the involvement of PAH in IL-22 and IL-17 production in asthmatic patients, as recent studies point out a participation of these cytokines in some endpoints of asthma." (PMID 25860963, 2015). "Acupuncture reduced the OVA specific IgE level as well as the Th17 cytokine levels including IL-17A, IL-17F, and IL-22 in the serum of the experimental asthma mice." (PMID 26612993, 2015). "In agreement with the presence of these endpoints in asthma, increased levels of IL-17A, IL-17F and IL-22 are found at the circulating and lung levels in allergic asthmatic patients as compared with controls." (PMID 25860963, 2015). "The presence of IL-22 and IL-17A in the sputum or peripheral blood is positively correlated with the severity of asthma." (PMID 26150907, 2015). "Th17 cytokines which included IL-17A, IL-17F, and IL-22 elevated obviously in asthma group compared to NC group (p < 0.05), and acupuncture exerted inhibitory effect on these cytokine levels (p < 0.05)." (PMID 26612993, 2015). "It has been shown that Th17 cells contribute to the asthma disease pathology and control many aspects of the disease through secretion of IL-17 and IL-22, which are frequently found in the airways of mouse model of asthma or in humans with asthma." (PMID 26612993, 2015). "Taking the transgenic approach, we sought to understand the functional role of IL-22 in the lung in the context of allergen-induced asthma." (PMID 25254361, 2014). "Others have reported that IL-22 is an anti-inflammatory cytokine with suppressive effects in asthma." (PMID 25091058, 2014). "We previously reported that the percentage of CD4+ T cells producing IL-17 and IL-22 (Th17 cells) is significantly greater in patients with active EGPA than in healthy controls or in patients with asthma, chronic eosinophilic pneumonia, or inactive EGPA." (PMID 25174446, 2014). "As further support for the increased activity of IL-22 in severe asthma, primary bronchial epithelial cells obtained from severe asthmatics expressed significantly higher levels of the IL-22 receptor." (PMID 24283210, 2013). "In this paper, we briefly summarize the roles of IL-22 in the regulation of allergic inflammation in asthma." (PMID 23577040, 2013).
asthma (continued). "In this paper, we summarize the recent progress on the roles of IL-22 in the regulation of allergic airway inflammation and discuss its therapeutic potential in asthma." (PMID 23577040, 2013). "It has been reported that IL-22 levels are increased in the sera of asthma patients and are positively correlated with disease severity." (PMID 23577040, 2013). "Further studies to elucidate the precise function of IL-22 at different stages of asthma pathogenesis will provide a great benefit for the development of a novel therapeutic approach for asthma." (PMID 23577040, 2013). "In contrast, it has been reported that the majority of IL-22-producing CD4+ T cell lines which are generated from lung biopsy specimens of asthma patients produce IFN-γ." (PMID 23577040, 2013). "The reason for the discrepancy is at present unclear and further studies to verify the cellular source of IL-22 in asthma patients are required." (PMID 23577040, 2013). "The question how exactly iNKT cells fit into the large picture of asthma-immunopathology remains unanswered and is even complicated by the recent observations that iNKT cells additionally produce IL-9, IL-17, and IL-22." (PMID 20976014, 2010). "Children with asthma had higher levels of IL-2 (p = 0.005), IL-5 (p < 0.001), IL-13 (p = 0.021), IL-17A (p < 0.001), IL-22 (p < 0.001), IL-33 (p < 0.001), TNF-α (p < 0.001), and lower levels of IL-10 (p = 0.046) and leptin (p < 0.001) compared to those without asthma." (PMID 39902293, 2024). "IL‐22 is released by several immune cells such as CD4+ T helper cells, γδT cells, NK cells and ILC3 cells and is implicated in the pathophysiology of various chronic inflammatory diseases including asthma and COPD and in mucosal‐associated infections." (PMID 39073027, 2024). "T2-low asthma is characterized by the activation of non-T2 inflammatory pathways, including helper T-lymphocytes type 1 (Th1) and/or Th17 cells, IL-6, IL-8, IL-17, and IL-22, and epithelial-derived cytokines." (PMID 37761964, 2023). "Th17 cells produce IL-17A, IL-17F, IL-21, IL-22, and TNF-α to perform their functions, and IL-17A and IL-17F are linked to severe asthma with neutrophil inflammation and responsible for corticosteroid resistance in asthma." (PMID 38203353, 2023). "Similar to the results in mice, the study found elevated serum and sputum IL-22 levels in asthma patients compared to healthy samples suggesting that IL-22 may be involved in the pathogenesis of asthma." (PMID 37377958, 2023). "Although we show that IL-22 positively regulates the allergic asthma inducing eosinophil survival and CD11c+CD11b+ cell infiltration, IL-22 plays no pro-inflammatory role in neutrophilic inflammation induced during the comorbidity asthma and acute pneumonia." (PMID 37445595, 2023). "Given the established role of IL-22 in epithelial physiology and in tissue remodeling, it might be an interesting target for the treatment of airway remodeling in asthma." (PMID 35386663, 2022). "Similar data suggests an involvement of IL-22 in subepithelial fibrosis in asthma." (PMID 35386663, 2022). "Th17 cytokines, including interleukin (IL)-17 and IL-22, play a role in neutrophilic inflammation in severe asthma and may be involved in airway remodeling." (PMID 35386663, 2022). "IL-17 and IL-22 are involved in neutrophilic inflammation in asthma." (PMID 35386663, 2022). "Karner J., Wawrzyniak M., Tankov S., Runnel T., Aints A., Kisand K.,Altraja A., Kingo K., Akdis C.A., Akdis M., Rebane A. Increased microRNA-323-3p in IL-22/IL-17-producing T cells and asthma:a role in the regulation of the TGF-β pathway and IL-22 production.Allergy." (PMID 35795226, 2022). "Overall, the precise role of IL-22 in asthma is still unclear, probably dependent on many parameters, such as the timing of action during the allergic process, the route of sensitization, as well as the immunological microenvironment regulating the Th22 response." (PMID 35386663, 2022).
asthma (continued). "In mouse models of asthma, the IL-22 level increases in the lung after airway challenge." (PMID 34836520, 2021). "Interestingly, a previous study demonstrated that Reg3γ induced by IL-22 inhibits allergic airway inflammation in asthma models." (PMID 34867960, 2021). "The ELISA Kit analysis of lung homogenates and BALF demonstrated that OVA-induced asthma, compared with phosphate buffered saline diluent control challenge of the BALB/c mice, was associated with significant elevation of the mean concentrations of IL-22." (PMID 34836520, 2021). "Moreover, it has been reported that serum levels of IL-22 are higher in patients with severe asthma than those seen healthy control subjects." (PMID 34485278, 2021). "For example, asthma induced by A. versicolor intratracheally manifested as a strong Th17 cell response along with IL-17A, IL-17F, and IL-22 expression, and co-exposure to the house dust mite and A. versicolor also resulted in a combination of Th2 and Th17 responses." (PMID 33441700, 2021). "By combining with IL-22RA1 and IL-10RB, IL-22 activates target cells to participate in inflammation, antimicrobial immunity and tissue repair, possibly playing an important role in the chronic airway inflammation of asthma." (PMID 34836520, 2021). "Finally, although we have detected the functional receptors of IL-22, the detailed downstream mechanisms of IL-22 in the OVA-induced asthma model should be further explored in the future studies." (PMID 34836520, 2021). "IL-22 has a protective role in liver diseases and graft versus host disease, an anti-apoptotic role in rheumatoid arthritis and an anti-inflammatory role in asthma." (PMID 33344684, 2020). "Furthermore, IL-22 mediated airway inflammation promotes atopic march which usually proceeds to asthma." (PMID 33042126, 2020). "In another study, IL-22 attenuated IL-25 production by lung epithelial cells and inhibited antigen-induced eosinophilic airway inflammation, underscoring that IL-22 might exert protective effects in asthma." (PMID 28231834, 2017). "This role of IL-21, IL-22 and IL-23 cytokines in inflamed lung airways may contribute to the persistence of airway remodelling and hence enhance asthma pathogenesis." (PMID 26772733, 2016). "Interleukin-22 (IL-22) is involved in lung diseases such as pneumonia, asthma and lung cancer." (PMID 27388918, 2016). "Furthermore, researchers have only begun to explore the role of IL-22 in allergy and asthma, but the effect of IL-22 is inconclusive." (PMID 26565810, 2015). "Animal models of asthma have shown that IL-17A and IL-22 can be deleterious or protective." (PMID 25860963, 2015). "Also, increased levels of IL-22 were found in the serum of asthmatic patients and in the lung tissues in experimental asthma in mice." (PMID 25254361, 2014). "However, in the context of allergen-induced asthma, IL-22 suppressed eosinophilic inflammation, mucus hyperplasia, AHR, and Th2 cytokine and chemokine production without affecting the systemic immune responses." (PMID 25254361, 2014). "Based on the findings of murine asthma models, IL-22 is produced by Th17 cells and LTi-like cells at the site of allergic airway inflammation and attenuates eosinophilic inflammation and AHR, presumably by inhibiting cytokine and chemokine production from lung epithelial cells." (PMID 23577040, 2013). "Taken together, these results suggest that IL-22 expression and signaling is associated with severe allergic airway disease rather than milder forms of asthma." (PMID 24283210, 2013). "TGF-β1 is known to promote EMT; however, other cytokines expressed in severe asthma with extensive remodeling, such as IL-22, may also contribute to this process." (PMID 24283210, 2013). "Interaction of Th17 with bronchial fibroblasts in asthma may induce a specific cytokine profile by bronchial fibroblasts and in turn may amplify specific Th17 cytokines such as IL-17 and IL-22." (PMID 24349168, 2013).
asthma (continued). "We have shown that the majority of IL-22-producing cells at the site of allergic airway inflammation are CD4+ T cells and that one third of the IL-22-producing CD4+ T cells produce IL-17A, suggesting that some of IL-22-producing CD4+ T cells in a murine asthma model are Th17 cells." (PMID 23577040, 2013). "In asthma patients, however, excessive production of IL-22 may lead to the progression of airway remodeling by enhancing the proliferation and migration of ASMCs." (PMID 23577040, 2013). "Furthermore, it has been reported that the levels of IL-22 mRNA are increased in peripheral blood mononuclear cells in asthma patients, and that the levels of IL-22 in sera tend to correlate with the severity of asthma." (PMID 23577040, 2013). "In addition, it has been shown that anti-IL-22 antibody enhances the production of IL-33, which also promotes Th2 responses, in different murine models of asthma." (PMID 23577040, 2013). "Despite these studies, our knowledge of IL-22 in asthma pathophysiology is still limited." (PMID 24032029, 2013). "It is well known that IL-22 is produced by Th17 cells and is required to develop allergic airway inflammation, and that IL-22 production has been reported to plays a supportive role in the pathogenesis of asthma." (PMID 23330224, 2012). "Although cytokines with strong proinflammatory potential such as TNF-α and IL-6 have meanwhile been implicated in at least several aspects of asthma pathogenesis, the effects of other TH17 cell derived factors such as IL-17F, IL-22, and IL-26 have only been investigated fragmentarily." (PMID 20976014, 2010). "There are several lines of evidence connecting IL-22 to asthma." (PMID 18315837, 2008). "Additionally, T2low asthma patients seem more prone to develop AR as they exhibit poorer lung function than T2high asthma patients and as some hallmarks of T2low inflammation, such as sputum neutrophilia, IL-17 and IL-22 levels, are particularly correlated to AR." (PMID 40082266, 2025). "Moreover, from a clinical perspective, neutrophilic inflammation in asthmatic patients has been observed regardless of steroid therapy as well as in steroid-naïve patients; cytokines frequently involved in T2-low asthma, such as IL-17A and IL-22, are often resistant to steroid action." (PMID 37189844, 2023). "First, the efficacy of the anti-IL-22 antibody fezakinumab was demonstrated in a randomized controlled trial in atopic dermatitis, a disease which shares many pathophysiological features with asthma and especially neutrophilic asthma (tissue remodeling, neutrophilic inflammation)." (PMID 35386663, 2022). "Furthermore, increased levels of IL-17 and IL-22 were insensitive to steroids, a characteristic frequently found in patients with neutrophilic airway inflammation and with airway remodeling and specific to severe asthma." (PMID 35386663, 2022). "Indeed, conflicting evidences have shown that IL-22 could have deleterious but also beneficial effects on airway epithelium in asthma." (PMID 35386663, 2022). "Taking advantage of a previously reported genetic signature of atopic dermatitis (AD) in patients who responded to anti-IL-22 (fezakinumab, FZ), they searched for such transcriptomic signatures in adults with severe asthma to determine whether they could be successfully treated with this biological." (PMID 35203504, 2022). "Interleukin-22 could play a protective role in an OVA-induced asthma model, by suppressing the inflammatory cell infiltration around bronchi and their concomitant vessels and airway hyperresponsiveness, which might associate with the expression of its heterodimer receptors." (PMID 34836520, 2021). "Interestingly, the increased smooth muscles in asthma might be a major source of pro-inflammatory asthma-relevant cytokines such as IL-13, IL-17, IL-22, IL-33, lymphopoietin, semaphorins, and CXC chemokines." (PMID 34834581, 2021).